JAK2 (Janus kinase 2)
Diseases named in the same sentence as JAK2 in open-access papers (continued):
Sharing a sentence is not in itself a finding about the gene and the disease.
triple-negative breast carcinoma (28 papers, 2014 to 2025). An invasive breast carcinoma which is negative for expression of estrogen receptor (ER), progesterone receptor (PR), and human epidermal growth factor receptor 2 (HER2). "Amplification of chromosome 9p24.1 targeting PD-L1, PD-L2, and JAK2 (PDJ amplicon) is present in subsets of triple negative breast cancers (TNBCs) and is associated with poor clinical outcomes." (PMID 36635351, 2023). "WWOX deficiency leads to the activation of JAK2/STAT3 signaling in metastatic triple negative breast cancer cells." (PMID 34140629, 2021). "Loss of WWOX upregulates the JAK2/STAT3 pathway for driving cancer metastasis in triple negative breast cancer cells." (PMID 31123603, 2019). "Loss of WWOX in triple-negative breast cancer cells leads to activation of the JAK2/STAT3 pathway for metastasis." (PMID 31123603, 2019). "Baicalin inhibits the protein expression of MMP9, TNF-α and JAK2 and their related signaling pathways in the treatment of triple-negative breast cancer." (PMID 40356970, 2025). "Conversely, HLF inhibits ferroptosis by promoting GSH in triple - negative breast cancer cells via the activation of the IL - 6/JAK2/STAT3 axis." (PMID 40371332, 2025). "In our study, we observed that HPV16 E7 expression in triple-negative breast cancer cells led to a significant reduction in the expression of JAK2 and STAT4, central components of cytokine-mediated immune response pathways." (PMID 40733498, 2025). "Recent studies revealed that USP21 affects JAK2/STAT3 axis in triple-negative breast cancer by indirect regulation of JAK2 stability." (PMID 39305962, 2024). "In particular, previous studies have shown that nintedanib modulates STAT3 activity, resulting in the apoptosis of triple-negative breast cancer cells as well as ameliorates IPF by inhibiting the JAK2/STAT3 pathway." (PMID 36055997, 2022). "Currently, ruxolitinib, a JAK1 and JAK2 inhibitor, is being investigated in treatment of primary and metastatic triple-negative breast cancer." (PMID 31060575, 2019). "Here, the authors illustrate that in triple negative breast cancer models Wwox suppresses metastasis and proliferation via the JAK2/STAT3 pathway." (PMID 30154439, 2018). "A recent report has suggested therapeutically targeting phosphoinositide 3 kinase (PI3K)/mTOR signaling in conjunction with suppression of JAK2/STAT5 in certain triple-negative breast cancers." (PMID 24913037, 2014). "The decrease in JAK2 observed in this study may impair the antitumor immune response, favoring disease progression, especially in more aggressive subtypes, such as triple-negative breast cancer." (PMID 40733498, 2025). "However, contrasting reports have shown that Siglec-1+ macrophages mediate immunosuppression via JAK2/STAT3 signaling in triple-negative breast cancer cells, suggesting that Siglec-1 plays complicated roles in different TMEs." (PMID 35418152, 2022). "However, in mice with triple-negative breast cancer, breast cancer cells were shown to promote PD-L1 expression in Siglec-1-positive macrophages by activating JAK2 signaling and promoting tumor immune escape." (PMID 35418152, 2022). "Balko JM proposed that JAK2 might be a therapeutic target for triple-negative breast cancers with amplification of JAK2, and specific JAK2 inhibitors could be used in combination with chemotherapy to inhibit this process, to reduce tumor-initiating stem cell-like cells and inhibit the tumor growth." (PMID 39669558, 2024). "In this study, expression of the E7 oncogene in triple-negative breast cancer cells led to a decrease in the expression of the STAT4, JAK2, and STAT3 genes, which are key mediators of the immune response." (PMID 40733498, 2025). "It is known that nintedanib rescues IPF via regulation of the JAK2/STAT3 pathway and induces apoptosis by inhibiting STAT3 in triple-negative breast cancer cells." (PMID 36055997, 2022).
triple-negative breast carcinoma (continued). "This also included the oncogene Janus kinase 2 (JAK2), which is co-amplified with CD274 (PD-L1) in classical Hodgkin lymphoma, triple negative breast cancer, and renal cell cancer as well as in NSCLC." (PMID 33576873, 2021). "While the JAK2/signal tranducer and activator of transcription 3 (STAT3) pathway plays a role in tumorigenesis, JAK2/STAT3 inhibitors have shown limited therapeutic efficacy in triple-negative breast cancer (TNBC)." (PMID 40649917, 2025).
diabetic nephropathy (26 papers, 2015 to 2025). "Activation of JAK-2 regulated pathway in human diabetic nephropathy was observed and this process leads to the development of glomerulosclerosis, fibrosis ultimately leading to renal failure." (PMID 41074478, 2025). "In fact, a phase 2 clinical trial demonstrated that the small molecule baricitinib, a selective JAK1 and JAK2 inhibitor, effectively lowered albuminuria in patients with type 2 diabetes and diabetic kidney disease." (PMID 41474553, 2025). "Another study in mouse with diabetic nephropathy demonstrated that the activation of JAK2/STAT3 signaling pathway in the kidney residual macrophages induced the release of proinflammatory factors and ROS, worsening kidney damage." (PMID 40700116, 2025). "In the glomerular sclerosis and matrix deposition of diabetic nephropathy, JAK2/STAT3 is the most important signal cascade involved in IL-6 transduction." (PMID 34054555, 2021). "The JAK1/JAK2 inhibitor protects autoimmune diabetes in experimental mice and improves the condition of diabetic kidney disease." (PMID 34067609, 2021). "In diabetic mice, enhanced expression of JAK2 selectively in glomerular podocytes increases pathological characteristics of diabetic kidney disease." (PMID 32375786, 2020). "A reduction in albuminuria was noted in participants with diabetic kidney disease in a phase 2 trial of the JAK1/JAK2 inhibitor baricitinib." (PMID 33343569, 2020). "In preclinical studies, the upstream JAK 2 protein has a known role in the development of diabetic nephropathy." (PMID 32375786, 2020). "A recent phase II trial of baricitinib, an oral inhibitor of JAK1 and JAK2, was found to decrease albuminuria at 24 weeks when compared to placebo in patients with diabetic kidney disease." (PMID 31396499, 2019). "Tubulointerstitial Jak-2 expression was strongly, inversely correlated with eGFR of patients with diabetic nephropathy." (PMID 31396499, 2019). "Podocyte hypertrophy observed in diabetic nephropathy (DN) may be related to IL-6 signaling through the activation of Janus kinase 2/signal transducer and activator of transcription 3 signaling pathway (JAK2/STAT3)." (PMID 41150807, 2025). "Enhanced JAK2 expression promotes the progression of diabetic nephropathy." (PMID 40365304, 2025). "Thus, we observed the effect of VHH-0031 on the expression of JAK2/STAT3 expression in diabetic nephropathy." (PMID 34054555, 2021). "Podocyte-specific JAK2 overexpression worsens diabetic kidney disease in mice." (PMID 32413585, 2020). "In a rat diabetic model, treatment with a JAK-STAT inhibitor (AG-490) reduced proteinuria; and overexpression of JAK2 in diabetic mouse podocytes elevated JAK-STAT pathway activity and exacerbated diabetic kidney disease." (PMID 41474553, 2025). "In vivo and in vitro experiments in diabetic nephropathy models have demonstrated that HDAC9 can induce podocyte apoptosis and renal injury through the JAK2/STAT3 pathway." (PMID 38528189, 2024). "The causal role of the pathway was supported by podocyte-specific overexpression of JAK2 and treatment of mice with an oral JAK inhibitor, ultimately leading to a phase 2 clinical trial in diabetic kidney disease." (PMID 34027630, 2021). "JAK2 and STAT3, playing key roles in the control of cell proliferation and inflammation, are the most important signal cascades involved in IL-6 transduction in the glomeruli and tubules of diabetic nephropathy." (PMID 34054555, 2021). "However, Jak-2 mRNA and protein expression was not enhanced in two mouse models of diabetes when compared to control mice, suggesting that differences in JAK-STAT pathway signaling between humans and mice may be one reason why mouse models fail to replicate advanced diabetic nephropathy." (PMID 31396499, 2019).
lymphoid neoplasm (26 papers, 2012 to 2025). A neoplasm composed of a lymphocytic cell population which is usually malignant (clonal) by molecular genetic and/or immunophenotypic analysis. "The PCM1 gene as partner in the chimera PCM1::JAK2 has been implicated in the pathogenesis of also other acute myeloid/lymphoid neoplasms whereas rearrangements of FGFR1 are rare." (PMID 38571499, 2024). "Likewise, loss of Llgl1 had not altered the course of murine lymphoid neoplasms induced by constitutive Notch, c-Myc or Jak2 expression." (PMID 37587260, 2023). "According to the TCGA database, JAK2 and STAT3 had high expression levels in a variety of malignancies, including lymphoid neoplasm DLBC." (PMID 32296013, 2020).
esophageal cancer (25 papers, 2014 to 2025). A primary or metastatic malignant neoplasm involving the esophagus. "In esophageal carcinoma, the JAK2/STAT3 signaling pathway can promote cell cycle arrest and mitigate the cytotoxic effects induced by radiation, functioning as a downstream component of the cGAS-STING pathway." (PMID 39975558, 2025). "Thereby, phloridzin repressed the progression of oesophageal cancer by acting as an antagonist to the JAK2/STAT3 signaling pathway." (PMID 40761486, 2025). "Another active Danshen component, cryptotanshinone, influences the Janus kinase-2/STAT3 signaling pathway, causing esophageal cancer cells to undergo apoptosis." (PMID 38146460, 2023). "Given that JAK2 was a promising target gene of miR-377-3p in esophageal cancer, we further probed the influence of miR-377-3p and JAK2 on CDDP resistance." (PMID 34307356, 2021). "Another study has verified that the progression of esophageal cancer was promoted by XIST-regulated miR-494/CDK6 axis to activate the JAK2/STAT3 signal pathway." (PMID 32127028, 2020). "Inhibition of Aurora-A in cells expressing mutant JAK2 abolishes the resistance to cisplatin, and enhances cisplatin-induced cell death in esophageal carcinoma cells." (PMID 25082261, 2014). "Therefore, phlorizin suppressed oesophagal cancer development by antagonizing the JAK2/STAT3 signaling pathway." (PMID 40761486, 2025). "Moreover, exosomal circ_0000337 enhances the cisplatin resistance of esophageal cancer cells by increasing Janus kinase 2 (JAK2) expression due to miR-377-3p inhibition." (PMID 36139487, 2022). "In addition, JaK2 acted as a carcinogenic factor through promoting cell growth and metastasis in esophageal cancer." (PMID 34307356, 2021). "All in all, these data indicated that miR-377-3p could decrease CDDP resistance in esophageal cancer cells by regulating JAK2." (PMID 34307356, 2021). "Therefore, the aim of the present study was to investigate the relationship between carbon ion inhibition of the proliferation and metastasis of esophageal carcinoma cells and the JAK2/STAT3 signaling pathway." (PMID 33330321, 2020). "This study demonstrated that root bark glycosides antagonize the JAK2/STAT3 signaling pathway, which can inhibit the development of esophageal cancer." (PMID 38273848, 2023). "Taken together, our results uncovered that exosomal circ_0000337 acted as a ceRNA of miR-377-3p to increase JaK2 expression, thereby enhancing CDDP resistance in esophageal cancer cells." (PMID 34307356, 2021). "In conclusion, our findings indicate that carbon ions inhibit the sustained activation of STAT3 through the JAK2/STAT3 pathway, which inhibits the migration and invasiveness of esophageal cancer cells." (PMID 33330321, 2020). "To uncover the mechanism through which genistein affects cyclical distribution and apoptosis in esophageal cancer cells, we tested the expression levels and phosphorylation levels of JAK1, JAK2, STAT1 and STAT3 in Eca-109 cells." (PMID 32276266, 2020).
myocardial ischemia (25 papers, 2018 to 2026). A disorder of cardiac function caused by insufficient blood flow to the muscle tissue of the heart. "Baicalin alleviates myocardial ischemia-reperfusion injury and inflammation caused by retinal ischemia-reperfusion injury in rats by inhibiting the phosphorylation levels of the JAK2/STAT3 signaling pathway." (PMID 39555089, 2024). "Mechanistically, L‐theanine has been shown to mitigate myocardial ischemia–reperfusion injury by suppressing apoptosis and oxidative stress via JAK2/STAT3 signaling." (PMID 41230384, 2025). "Studies have shown that JUN is closely related to the JAK2/STAT3 signaling pathway and the PI3K-Akt signaling pathway, and it can effectively treat acute renal injury caused by myocardial ischemia." (PMID 39339421, 2024). "It reduces myocardial ischemia/reperfusion injury by activating Janus kinase 2 (JAK2) and suppressing pro-inflammatory and apoptotic responses." (PMID 39796512, 2024). "Myocardial ischemia, hypoxia, and reperfusion are considered as stressors that stimulate the production of related cytokines, thus activating the JAK2/STAT3 signaling pathway and providing cardioprotection." (PMID 35263202, 2022). "Nonetheless, it is also demonstrated that ER reduces the chances of myocardial ischemia/reperfusion (I/R) injury in the SD rodent by stifling support of incendiary and myocardial apoptosis responses by modulating Janus kinase 2 (JAK2) pathway." (PMID 33414838, 2020). "JAK2/STAT3 activation can attenuate mitochondrial oxidative damage induced by myocardial ischemia/reperfusion injury and maintain mitochondrial function." (PMID 29441065, 2018). "Berberine was found to activate the Silent Information Regulator-1 (SIRT1) signaling pathway following myocardial ischemia/reperfusion, as well as the Janus kinase 2/signal transducer and activator of transcription (JAK2/STAT3) signaling pathway, leading to reduced apoptosis and oxidative stress." (PMID 39202856, 2024). "Similarly, other researchers demonstrated that JAK2/STAT3 signaling was effectively up-regulated during myocardial ischemia and aggravated injury." (PMID 35655588, 2022). "For example, Strychnine regulates oxidative stress and apoptosis by activating JAK2/STAT3 signaling pathway, thereby preventing myocardial ischemia–reperfusion injury." (PMID 39940217, 2025). "Lan Wu also demonstrated that ROS, through the activation of the JAK2/STAT3 pathway, exhibits cardioprotective function in early cardiac ischemia–reperfusion injury." (PMID 39877839, 2025). "In myocardial ischemia and infarction models, the protective effects of GSH-inducing substances were abolished by AG490 treatment, suggesting a role for JAK2/STAT3 in modulating GSH levels." (PMID 40802001, 2025). "In addition, it can also promote the secretion of IL-10 and activate the JAK2/STAT3 signaling pathway, showing pharmacological effects in alleviating myocardial ischemia/reperfusion injury." (PMID 39942654, 2025). "In an animal model of myocardial ischemia/reperfusion, DEX alleviated myocardial mitochondrial apoptosis through a pathway involving the lncRNA HCP5/miR-29a/MCL1 axis and activation of Janus kinase 2/signal transducer and activator of transcription 3 signaling." (PMID 39881865, 2024).
Arthritis (24 papers, 2010 to 2025). Inflammation of a joint. "Among the polymorphisms found more frequently in AS patients with arthritis, JAK2 rs7857730, IL-23R rs11209008 and rs10489630, CYP1B1 rs1056836, NELL1 rs8176786, KL rs564481, MEFV rs224204, IL-2RB rs743777, and IL-1A rs1800587 have been described." (PMID 35629038, 2022). "A possible role for Janus kinase (JAK)-inhibitors has been suggested from animal models of ILD associated with arthritis as the JAK2 isoform specifically mediates TGF-beta signaling and the activation of myofibroblasts, and has been advocated in the molecular pathophysiology of RA-ILD." (PMID 37007765, 2023). "Blockade of JAK2 associated with these major cytokine receptors may affect the subsequent expression or production of downstream cytokines during arthritis and may be responsible for some of the results shown here." (PMID 21510883, 2011). "It was also reported that the Ershiwuwei Lvxue pill (ELP) that is Tibetan traditional medicine, reduced collagen-induced arthritis through JAK2/STAT3-signaling pathway inhibition." (PMID 33917914, 2021). "In an arthritis model, it has been discovered that the Jak2/Stat3 pathway activates the transcription of antiapoptotic genes, such as Bcl2, and rescues chondrocytes from apoptosis." (PMID 27314053, 2016). "Furthermore, JAK2 inhibitor has been considered a promising therapeutic reagent for arthritis treatment." (PMID 33917914, 2021). "Collagen antibody-induced arthritis (CAIA) and collagen type II (CII)-induced arthritis (CIA) were established before the oral administration of a small-molecule JAK2 inhibitor, CEP-33779, twice daily at 10 mg/kg, 30 mg/kg, 55 mg/kg or 100 mg/kg over a period of 4 to 8 weeks." (PMID 21510883, 2011). "Curcumin attenuated the severity of arthritis and reduced synovial hyperplasia by modulating the inc00052/miR-126-5p/PIAS2 pathway through the JAK2/STAT3 signaling mechanism, thereby providing protective effects against RA." (PMID 39974740, 2025). "The observed amelioration of adjuvant-induced arthritis demonstratedmore robust control of the STAT3/p-STAT3 and JAK2/p-JAK2 pathways,indicating that these pathways hold significant promise as therapeuticstrategies for the management of RA." (PMID 39470172, 2024). "Paeoniflorin can regulate signaling pathways (GPCR pathway, MAPKs/NF-κB pathway, PI3K/Akt/mTOR pathway, JAK2/STAT3 pathway, TGFβ/Smads, etc.)in experimental arthritis FLS." (PMID 37033930, 2023). "Abnormal activation of the JAK2/STAT3 pathway is closely involved in numerous inflammatory diseases progression, including arthritis, hepatitis, nephritis, and UC." (PMID 35220895, 2022). "Pharmacodynamic inhibition of JAK2 reduced mean paw edema and clinical scores in both CIA and CAIA models of arthritis." (PMID 21510883, 2011). "PD inhibition of JAK2 reduced mean paw edema and clinical scores in both the CIA and CAIA models of arthritis." (PMID 21510883, 2011). "Furthermore, notopterol reduces inflammation by binding directly to three essential sites, in the JAK2/3 kinase domains, resulting in JAK-STAT signaling suppression in arthritis." (PMID 38532994, 2024). "Furthermore, study found that complete freund adjuvant (CFA)-induced arthritis triggered TNF-α secretion, increased JAK2 levels, and decreased transforming growth factor-β (TGF-β) levels in tissue homogenates." (PMID 39484157, 2024). "Furthermore, the promotion of p-JAK2 and p-STAT3 was observed in the synovial tissues of MSU crystal-induced arthritis rats according to Yang's study." (PMID 36248423, 2022). "LMT-28 could alleviate arthritis and acute pancreatitis in mice, reduce the secretion of TNF-α in serum, and inhibit IL-6-induced phosphorylation of Stat3, gp130 and JAK2 proteins." (PMID 34955842, 2021). "Recent preclinical evidence indicate selective Syk inhibitors that have no activity against Jak2 can be efficacious in models of arthritis." (PMID 26756335, 2016).